IRAK4 (interleukin 1 receptor associated kinase 4)
Diseases named in the same sentence as IRAK4 in open-access papers (continued):
Sharing a sentence is not in itself a finding about the gene and the disease.
Splenomegaly (6 papers, 2016 to 2025). Abnormal increased size of the spleen. "In addition, a mutation in IRAK1 or IRAK4 prevents the splenomegaly, ANA production, hypergammaglobulinemia and GN in ABIN1[D485N] mice." (PMID 31354711, 2019). "Elimination of IRAK4 activity prevented both mild and severe splenomegaly exhibited by Sle1 and Sle1Tg7 mice, respectively." (PMID 31354711, 2019). "Our study provides evidence that mice susceptible to NPSLE with mutated IRAK4 kinase domain improved their pathology, including reduced splenomegaly, absence of anti-dsDNA antibody and better memory function congruent with hippocampal function." (PMID 39014006, 2024). "In contrast, the pMo in the blood of control ABIN1[D485N] mice not given the IRAK4 inhibitor continued to increase, and these mice developed splenomegaly, auto-antibodies, glomerulonephritis, liver pathology, and lung inflammation." (PMID 31694920, 2019). "Neither ABIN1[D485N] × IRAK4[D329A] mice nor ABIN1[D485N] × IRAK1[D359A] mice developed splenomegaly and, consistent with these observations, the levels of ANAs, dsDNA Abs, and other IgGs and IgM in the serum of these mice were similar to WT mice." (PMID 27807192, 2016).
acute myeloid leukemia (5 papers, 2022 to 2025). Acute myeloid leukemia (AML) is a group of neoplasms arising from precursor cells committed to the myeloid cell-line differentiation. "The oncogenic long form of IRAK-4 (IRAK4-L) has been found to be overexpressed in acute myeloid leukemia (AML) and myelodysplastic syndromes (MDS) and portends a worse prognosis." (PMID 37954584, 2023). "In this preclinical study, we assessed the IRAK4 inhibitor emavusertib (CA4948) in combination with the MCL1 inhibitor S63845, the BCL2 inhibitor venetoclax, and the HSP90 inhibitor PU-H71 in the treatment of acute myeloid leukemia and investigated the associated biomarkers of response." (PMID 38666914, 2024). "(E) IRAK4 expression in sorted HSCs (Lineage –ve, CD34+, CD38−) cells from MDS/acute myeloid leukemia (AML) cases (N=9) and controls (N=5)." (PMID 36040792, 2022).
B-cell lymphomas (5 papers, 2022 to 2024). "Preclinical data suggest that the IRAK4 inhibitor emavusertib results in lymphoma cell death in vitro with MYD88-mutated indolent B-cell lymphomas as a single agent and as a combination partner with BTK or PI3K inhibitors in unselected populations." (PMID 38068428, 2023). "Persistent survival signaling though downstream molecules such as interleukin 1 receptor-associated kinase 4 (IRAK-4), an integral part of the “myddosome” complex, has been shown to be constitutively active in B-cell lymphoma patients treated with BTK inhibitors." (PMID 37954584, 2023). "Due to the inability of current therapeutics to cure the majority of B-cell NHLs and myeloid neoplasms and the eventual development of drug resistance, the therapeutic targeting of IRAK-4 is a merited treatment strategy." (PMID 37954584, 2023). "Persistent IRAK-4 signaling in the setting of treatment with BTK inhibitors has been shown in B-cell lymphomas making IRAK-4 inhibition an attractive therapeutic target." (PMID 37954584, 2023). "The orally bioavailable IRAK-4 inhibitor, emavusertib, is emerging as an efficacious treatment in the therapeutic armamentarium against B-cell NHL and MDS/AML." (PMID 37954584, 2023). "In this review article, we discuss the currently available pre-clinical and clinical data of emavusertib, a selective, orally bioavailable IRAK-4 inhibitor in the treatment of R/R B-cell lymphomas and myeloid malignancies." (PMID 37954584, 2023). "Emerging evidence is demonstrating the therapeutic benefit of IRAK-4 inhibition in B-cell lymphomas, along with possibly reversing BTK inhibitor resistance." (PMID 37954584, 2023). "The central role of IRAK-4 in aberrant TLR/innate immune signaling in B-cell NHL and myeloid malignancies makes emavusertib a promising therapeutic agent that can curtail pro-tumoral inflammation and synergize with other therapies to enhance malignant cell apoptosis." (PMID 37954584, 2023). "Emavusertib, a selective IRAK-4 inhibitor, is under clinical investigation to overcome the persistent survival signaling through IRAK-4 in B-cell lymphomas." (PMID 38397043, 2024). "Preclinical studies have shown the anti-B cell NHL and anti-AML/MDS therapeutic efficacy of IRAK-4 inhibition." (PMID 37954584, 2023).
COVID-19 (5 papers, 2021 to 2024). A disease caused by infection with severe acute respiratory syndrome coronavirus 2. "Overall, COVID-19 severity appears to be similar in patients with MyD88/IRAK-4 deficiency and in those with TLR7 deficiency." (PMID 36880831, 2023). "IRAK4 is upregulated in SARS-CoV-2 infection, and IRAK4-based silencing therapy has been proposed as a method to treat macrophage inflammatory and glycolytic reprogramming in COVID-19." (PMID 38632526, 2024). "We also searched for an enrichment in rare (gnomAD frequency <10−3) pLOF variants of IRAK4 and MYD88 in 3,269 patients with critical COVID-19, and 1,373 controls with asymptomatic or mild SARS-CoV-2 infection from the CHGE." (PMID 36880831, 2023). "Here a case is made for considering IRAK4 or IRF5 inhibitors as potential therapies for the “cytokine storm” of COVID-19." (PMID 33936053, 2021). "Ongoing clinical trial (NCT04575610) is investigating the efficacy of IRAK4 inhibition in patients who are hospitalized with COVID-19 ARDS." (PMID 34248990, 2021). "The bacterial infection phenotype of MyD88 or IRAK-4 deficiency is clearly recessive, but we analyzed possible co-dominance for the COVID-19 phenotype in 20 unvaccinated household relatives heterozygous for MYD88 or IRAK4 (mean age: 32.4 yr, SD: 12.3 yr, range: 10–52 yr)." (PMID 36880831, 2023). "Some cytokine inhibition strategies are being investigated for COVID-19; however, IRAK4 may thus provide an important therapeutic target to consider for CRS in COVID-19, given its role in innate immunity and TLR signaling." (PMID 34248990, 2021). "The potential impact of a successful therapeutic target, such as IRAK4, in COVID-19 could allow for decreased overall mortality, reduced time with mechanical ventilation, decreased time to clinical improvement, and shorter hospitalization stay." (PMID 34248990, 2021).
diffuse large B-cell lymphoma (5 papers, 2020 to 2024). "Previous findings suggest a therapeutic potential for IRAK4 inhibitors for the activated B-cell-like (ABC) subtype of diffuse large B-cell lymphoma (DLBCL) presenting with MYD88 mutations, as well as for autoimmune disorders and other malignancies that depend on TLR signaling." (PMID 31197259, 2020). "In particular, efficient IRAK4 inhibitors of activated B‐cell subtype of human diffuse large B‐Cell lymphoma (DLBCL) are being developed." (PMID 36214464, 2022).
glioma (5 papers, 2017 to 2025). A benign or malignant brain and spinal cord tumor that arises from glial cells (astrocytes, oligodendrocytes, ependymal cells). "In glioblastomas, IRAK4 (Interleukin 1 Receptor Associated Kinase 4) is upregulated after temozolomide (TMZ) treatment in glioma cells and mediates Toll-like receptor signaling and chemoresistance." (PMID 40338274, 2025). "Only a previous study identified that IRAK4 leads to chemoresistance to temozolomide in glioma cells." (PMID 35211171, 2022). "Meanwhile, the fact that the survival of brain tumors such as LGG can be determined by miR-132 and the validated target gene IRAK4 and the incidence of epilepsy is much higher in low-grade gliomas than in high-grade gliomas remind us whether miR-132/212 get involved in brain tumor-induced epilepsy." (PMID 28380454, 2017).
ischemia (5 papers, 2014 to 2021). A hypoperfusion of the BLOOD through an organ or tissue caused by a PATHOLOGIC CONSTRICTION or obstruction of its BLOOD VESSELS, or an absence of BLOOD CIRCULATION. "There was a significant positive correlation between TLR2, TLR4, IRAK3 and IRAK4 expression and the degree of ischemia as assessed by serum lactate levels and the time until return of spontaneous circulation." (PMID 27260481, 2016). "The protective mechanism of ischemic postconditioning was investigated by comparing its effects on apoptosis, production of the neurotoxic cytokine IL-1β and the transcription and expression of TLR2, TLR4 and IRAK4 in the 2 and 4.5 hour ischemia groups." (PMID 24460643, 2014). "The addition of inflammatory medium OGD + LPS or OGD + IL-4 both resulted in significantly lower calcein RFU compared with the untreated normoxia control; however, the media with addition of ND2158 reversed the RFU, suggesting the inhibition of IRAK4 can increase neuronal survival in ischemia." (PMID 33573200, 2021). "HO-1 activator CoPP can reduce the expressions of TLR2, TLR4, IRAK-4 and TRAF6, and markedly increases the expressions of TLR negative regulators, such as SOCS-1, IRAK-M and SHIP-1, in ischemia/reperfusion liver injury in rat." (PMID 29057806, 2017). "No significant influence of ischemic postconditioning on IRAK4 was found in the 4.5 hour ischemia group." (PMID 24460643, 2014).
lymphoma (5 papers, 2021 to 2025). A malignant (clonal) proliferation of B- lymphocytes or T- lymphocytes which involves the lymph nodes, bone marrow and/or extranodal sites. "The IRAK4 inhibitor emavusertib was tested in two marginal zone lymphoma models (VL51 and Karpas1718) and their derivatives with secondary resistance to PI3K and BTK inhibitors." (PMID 36675328, 2023). "Therefore, predicting such gene (IRAK4) as another lymphoma biomarker is quite reasonable." (PMID 34899868, 2021). "CA-4948 is a specific inhibitor of IRAK4 that is now being tested in clinical trials in MDS/AML and lymphomas (ClinicalTrials.gov: NCT04278768; NCT03328078) and in preliminary findings has shown a tolerable safety profile." (PMID 36040792, 2022). "IRAK4 (ENSP00000390651) is also a participant in the IRAK signaling pathway, which is essential for the pathogenesis of lymphoma." (PMID 34899868, 2021).
myelodysplastic syndrome (5 papers, 2022 to 2025). A clonal hematopoietic disorder characterized by dysplasia and ineffective hematopoiesis in one or more of the hematopoietic cell lines. "IRAK4 overexpression is associated with adverse clinical features in human myelodysplastic syndromes (MDS), and its inhibition leads to reduction in MDS clones in vivo." (PMID 36040792, 2022). "The molecule used to block IRAK4, CA-4948 – also known as Emavusertib – is currently being evaluated in clinical trials for myelodysplastic syndromes and other types of blood cancer." (PMID 36040792, 2022). "In myelodysplastic syndrome (MDS) and AML, aberrations of mRNA splicing are frequently observed to produce an alternative splice product of IRAK4 which includes exon 4 (IRAK4-L)." (PMID 36991452, 2023).
asthma (4 papers, 2011 to 2022). "The homozygous variant of IRAK4 (IL-1 receptor-associated kinase-4), rs4251513, has been constantly associated with post-bronchiolitis wheezing episodes and asthma medication use at school-age." (PMID 36362786, 2022). "We further identify a conserved C-lobe surface on IRAK3 that harbors asthma-associated mutations and closely resembles the previously reported IRAK4 homodimer interface." (PMID 33238146, 2021). "By analyzing asthma-associated mutations, we identify an evolutionarily conserved surface on IRAK3 that could form an interaction interface with IRAK4, suggesting a model for the negative regulation of IRAK4 by IRAK3." (PMID 33238146, 2021).
complement deficiencies (4 papers, 2019 to 2025). "The most common defects include antibody and complement deficiencies, congenital asplenia, or innate immune signaling disorders involving MYD88 and IRAK4." (PMID 41510457, 2025). "Apart from antibody deficiency, differential diagnostic considerations should include complement deficiency, asplenia or splenic impairment as in sickle cell disease, and defects in innate immunity such as Toll-like/IL1R defects e.g., IRAK4/MyD88 deficiency." (PMID 38933494, 2024). "In PIDs that do not affect the lymphoid compartment (CGD, IRAK4 and complement deficiencies) no aberrant populations were identified, indicating that this tube is not useful for these categories." (PMID 30886612, 2019).
myeloid malignancies (4 papers, 2021 to 2024). "Mutations in spliceosome genes U2AF1 and SF3B1 have been linked to the expression of oncogenic IRAK4 isoforms in myeloid malignancies." (PMID 38666914, 2024). "This preliminary data also supports the evaluation of IRAK-4 inhibition for the treatment of myeloid neoplasms, particularly if they harbor mutations in splicing factors." (PMID 37954584, 2023). "Mutations in the spliceosome genes U2AF1 and SF3B1 have been linked to the expression of oncogenic IRAK4 isoforms in myeloid malignancies, and may impose sensitivity to IRAK4 inhibition." (PMID 38666914, 2024). "In myeloid malignancies such as MDS and AML, spliceosome mutations of SF3B1 or U2AF1 lead to formation of hypermorphic IRAK-4 isoforms (IRAK-4-L) which activate myddosomal signaling promoting cell survival." (PMID 37954584, 2023). "Our observations that alternative splicing of genes in the MyD88 dependent pathway are important candidates in oncogenesis agree with the recent description of oncogenic IRAK4 isoforms, albeit in myeloid malignancies." (PMID 34163463, 2021). "Hypomethylating agents such as decitabine and azacitidine with or without the BCL-2 inhibitor venetoclax rarely lead to long-term disease control in myeloid neoplasms, thus the addition IRAK-4 inhibition may deepen and prolong responses in patients with myeloid malignancies." (PMID 37954584, 2023). "Emavusertib (CA4948), a multi-kinase inhibitor of IRAK4 and FLT3, has been proposed for the treatment of B-cell lymphoma and myeloid malignancies." (PMID 38666914, 2024).
allergic rhinitis (3 papers, 2011 to 2023). Inflammation of the nasal mucous membranes caused by an IgE-mediated response to external allergens. "In this study, we aimed to evaluate the contribution of single nucleotide polymorphisms (SNPs) in the IRAK-4 gene region to allergic rhinitis (AR) susceptibility in a Chinese population-based case-control association analysis." (PMID 21738793, 2011). "We attempted to determine whether the polymorphisms in the Interleukin-1 receptor-associated kinase-4 (IRAK-4) gene are associated with allergic rhinitis (AR) in the Han Chinese population." (PMID 21738793, 2011).
antibody deficiency (3 papers, 2023 to 2025). "These primary immunodeficiencies included antibody deficiencies, complement defects (C2 or C3), congenital asplenia, and signaling defects in MYD88 and IRAK4." (PMID 41510457, 2025). "If any of these mechanisms, including complement or antibody deficiency, problems in the TLR signaling cascade (such as MYD88 or IRAK4 mutations), or congenital asplenia, are lacking in children, they are at a higher risk of recurrent or severe IPD." (PMID 41510457, 2025).
atopic dermatitis (3 papers, 2022 to 2024). "Toll-like receptor–driven and interleukin-1 (IL-1) receptor–driven inflammation mediated by IL-1 receptor–associated kinase 4 (IRAK4) is involved in the pathophysiology of hidradenitis suppurativa (HS) and atopic dermatitis (AD)." (PMID 37957373, 2023).
central nervous system lymphoma (3 papers, 2025). "Targeted drugs such as Bruton’s tyrosine kinase (BTK) inhibitors, interleukin-1 receptor-associated kinase-4 inhibitors, and immunomodulators including lenalidomide and pomalidomide had also show certain efficacy in central nervous system lymphoma." (PMID 40978033, 2025).
colorectal cancer (3 papers, 2021 to 2023). A primary or metastatic malignant neoplasm that affects the colon or rectum. "Similarly, activated IRAK4 (p-IRAK4) was associated with poor prognosis in colorectal cancer (CRC) patients at stage IIb–IV more notably than in patients at stage I-II." (PMID 37108068, 2023).
encephalitis (3 papers, 2021 to 2025). An acute inflammatory process affecting the brain parenchyma. "Our patient’s atypical clinical manifestation and development of anti-NMDAR encephalitis in infancy led us to sequence his whole exome and identify IRAK4 deficiency." (PMID 33083971, 2021). "In the current study, we report a rare case of IRAK4 deficiency presenting with severe neurological sequelae associated with anti-NMDAR encephalitis and human herpes virus 6 (HHV6) reactivation." (PMID 33083971, 2021). "The limitation of our study is a lack of direct evidence that demonstrates the relationship between IRAK4 deficiency and development of anti-NMDAR encephalitis and/or HHV6 reactivation." (PMID 33083971, 2021). "It highlights genetic defects such as deficiencies in MyD88, IRAK-4, NEMO, and TLR3, which lead to distinct clinical phenotypes, for example, increased susceptibility to bacterial infections or herpes simplex virus type-1 (HSV-1) encephalitis." (PMID 41369391, 2025).
gout (3 papers, 2019 to 2025). A condition characterized by painful swelling of the joints, which is caused by deposition of urate crystals. "Given this pattern, we explored whether targeting IRAK4—a common downstream mediator of TLR signaling—could attenuate the inflammatory response associated with gout." (PMID 40709261, 2025). "This study addresses that gap by investigating the effect of IRAK4 inhibition in an in vitro gout model." (PMID 40709261, 2025). "Our findings showed that xanthine stimulation upregulated XDH and pro-inflammatory cytokines, whereas IRAK4 inhibitor treatment significantly suppressed both XDH expression and cytokine production, indicating that IRAK4 signaling may also contribute to liver inflammation in the context of gout." (PMID 40709261, 2025).
herpes simplex encephalitis (3 papers, 2017 to 2025). Herpes simplex virus encephalitis (HSE) is caused by the infection of the central nervous system by Herpes simplex virus (HSV) that could have a devastating clinical course and a potentially fatal outcome particularly with delay or lack of treatment. "Novel variants were identified, including IRAK4 c.277delT (p.F93fsX26), not previously reported, and SNORA31 (n.36T>C), previously seen in Saudi Arabia, now found in a Moroccan case of herpes simplex encephalitis." (PMID 41209815, 2025).
intracerebral hemorrhage (3 papers, 2015 to 2021). A cerebrovascular disorder characterized by bleeding into one or both cerebral hemispheres including the basal ganglia and the cerebral cortex. "Recently, miR-367 was described to regulate IRAK4 in primary microglia cells that negatively modulated the inflammatory response of microglia in an intracerebral hemorrhage." (PMID 34445350, 2021). "Similarly, knocking down IRAK4 in microglia decreased the IRAK4 expression and inhibited the activation of NF-ĸB and the downstream production of proinflammatory factors, thus reducing the intracerebral hemorrhage (ICH) induced microglia activation and inflammatory cytokines release." (PMID 34863246, 2021).